RN7SL403P (RNA, 7SL, cytoplasmic 403, pseudogene)
Gene: Miscellaneous RNA gene on chromosome 6 (43,036,196 to 43,036,500, reverse strand). Ensembl gene ENSG00000240625.
Homologues: Orthologues: macaque Metazoa_SRP (39% identical). Paralogues in human: Metazoa_SRP (67% identical), RN7SL1 (65% identical), RN7SL2 (64% identical), RN7SL3 (64% identical), Metazoa_SRP (64% identical), RN7SL559P (63% identical), RN7SL664P (63% identical), RN7SL126P (63% identical), RN7SL186P (63% identical), RN7SL288P (63% identical), RN7SL386P (63% identical), RN7SL113P (62% identical), and 697 more.